LINC00431 (long independently transcribed non-coding RNA 431)
Gene: Transcribed unprocessed pseudogene on chromosome 13 (110,989,980 to 110,990,138, forward strand). Ensembl gene ENSG00000225760.
Diseases named in the same sentence as LINC00431 in open-access papers:
LINC00431 is named in the same sentence as 10 diseases in open-access papers, as found by Europe PMC text mining. Sharing a sentence is not in itself a finding about the gene and the disease.
LINC00431 shares sentences with these, for which no sentence is quoted: cancer (1 paper); colon cancer (1); colorectal cancer (1); esophageal cancer (1); gastric carcinoma (1); hepatocellular carcinoma (1); myeloma (1); non-small cell lung carcinoma (1); ovarian carcinoma (1); pancreatic cancer (1).